ALB (albumin)
Diseases named in the same sentence as ALB in open-access papers (continued):
Sharing a sentence is not in itself a finding about the gene and the disease.
kidney disease (continued). "It has been discovered that albumin corresponds more closely with the development of glomerular disorder in hypertension and renal disease in diabetes, even when tubular/overflow proteinuria is present." (PMID 36415443, 2022). "In the present study, we examine the effect of TRPC6 inactivation in a four-week albumin overload model of kidney disease in Sprague Dawley rats." (PMID 35805070, 2022). "Prevalent estimated glomerular filtration rate < 60 ml/min/1.73 m2 or urinary albumin creatinine ratio ≥ 30 mg/g was defined as kidney disease." (PMID 35802581, 2022). "In one study, albumin was suggested as a self-antigen in renal disease with proteinuria, where breakdown of the glomerular filtration barrier results in access of albumin to kidney tissue." (PMID 35563816, 2022). "The Kidney Disease: Improving Global Outcomes clinical practice guidelines for CKD recommend nephrology referral for eGFR < 30 ml/min/1.73m2 or for urinary albumin/creatinine ratio ≥ 300 mg/g." (PMID 36434513, 2022). "Although a high level of albumin (above 30 mg/g) is clinically the earliest sign of kidney disease (even if the GFR is above 60), correlations between DC parameters and albumin (mg/L) were not statistically significant in the present study." (PMID 35566743, 2022). "We consider that in patients with renal disease, the level of plasma albumin decreases due to proteinuria, and then the colloid osmotic pressure in the blood vessels decreases, and the interstitial fluid increases, resulting in edema." (PMID 36513626, 2022). "Sphingomyelin, a type of sphingolipid found in cellular membranes, has been reported as a significant biochemical covariate of urinary albumin excretion in renal disease." (PMID 36422264, 2022). "Our results show that cubilin glycosylation can impede albumin interaction thus potentially contributing to albuminuria observed in kidney disease." (PMID 35970386, 2022). "Renal diseases, malignancy, and serum albumin level were also identified as key factors for readmission, consistent with previous studies." (PMID 35284804, 2022). "In this study, F1 was not statistically significant when comparing G0, G1, and G2, although there are several studies that describe dogs with kidney disease, albumin is excreted in greater quantity." (PMID 36467666, 2022). "SERAP is six-variable survival score, and takes the number of emergency admissions last year, age, history of malignancy, history of renal diseases, serum creatinine level, and serum albumin level during index admission into consideration." (PMID 35284804, 2022). "Determining early warning parameters for decreased glomerular filtration rate and urinary albumin excretion in kidney disease is of great importance." (PMID 36615770, 2022). "And it decreased with aging for several potential reasons such as hepatic or renal disease and dysphagia, supported by some studies estimating albumin level reduction by 20% in patients over 70 years old." (PMID 36300178, 2022). "Alport mice showed severe proteinuria and, in other kidney disease model mice, urinary albumin is reported to increase CL-1 expression in PECs, therefore we examined the effect of albumin on CL-1 expression in human proximal tubular cells." (PMID 35271660, 2022). "Current guidelines on CKD from the Kidney Disease Improving Global Outcomes (KDIGO) recommend measuring albuminuria to quantify proteinuria, since albumin is the predominant protein in the vast majority of proteinuric kidney diseases." (PMID 36290476, 2022). "In the Modification of Diet in Renal Disease (MDRD) study, low albumin independently predicted all-cause mortality in stage 3 and 4 CKD patients over a 10-year follow-up." (PMID 35889807, 2022). "The same guidelines recommend treating T2DM patients with DKD (estimated GFR ≥ 25 mL/min/1.73 m2 and urinary albumin ≥ 300 mg/g creatinine) with canagliflozin, empagliflozin, or dapagliflozin to reduce renal disease progression and CV events." (PMID 35409011, 2022).
kidney disease (continued). "First, plasma BNP and urinary albumin levels, which are established markers for cardiovascular and renal disorders, respectively, were independently correlated with each other." (PMID 37234386, 2022). "The serum albumin level is part of a standard panel of parameters determined in the clinical laboratory, e.g., in liver and kidney disease." (PMID 35566209, 2022). "Traditional techniques, such as the histological assessment of collagen deposition and quantification of serum/urine biomarkers (e.g., creatinine, blood urea nitrogen (BUN), albumin, and cytokines), are the most commonly used to diagnose kidney disorders." (PMID 35055081, 2022). "Prevalent eGFR < 60 mL/min/1.73 m2 or urinary albumin/creatinine ratio ≥ 30 mg/g was defined as kidney disease in this study." (PMID 36290476, 2022). "Tube feeding, low serum albumin and renal disease change the intestinal flora, and furthermore, low serum albumin provokes intestinal edemas." (PMID 34001039, 2021). "We used albumin (half-life: 20 days) as a marker of long-term liver (or renal) disease and ALT (half-life: 47 h) as an indicator of more recent changes to hepatic function." (PMID 34574044, 2021). "More recently the KDIGO (Kidney Disease: Improving Global outcomes) classification was enriched with the addition of urinary albumin to creatinine ratio (UACR) meant for CKD staging and prognostication." (PMID 34896941, 2021). "The mean serum albumin of HD patients in our study (3.72 ± 0.48 g/dl) was lower than the recommended target of 4 g/dl by the National Kidney Foundation Kidney Disease Outcomes Quality Initiative." (PMID 34123420, 2021). "CKD was diagnosed based on the estimated glomerular filtration rate using the ‘Modification of Diet in Renal Disease’ equations and the presence of albuminuria estimated by the albumin-to-creatinine ratio." (PMID 34886001, 2021). "HRs were adjusted for age, sex, body mass index, cardiovascular disease, dialysis modality, primary kidney disease, use of antithrombotic medication, systolic blood pressure, albumin, C-reactive protein and residual GFR." (PMID 34134634, 2021). "Moderately increased albuminuria, defined by an albumin to creatinine ratio (ACR) > 30 mg/g, is an indicator of subclinical organ damage associated with a higher risk of cardiovascular and renal disease." (PMID 34356333, 2021). "In the present work, we succeeded in designing a magnetic nanobiosensor by hematite nanorod for the first time with higher sensitivity than laboratory methods for measuring albumin in urine to detect kidney diseases." (PMID 34712427, 2021). "Micro-albumin and urinary protein measurement also provide a feasible means of performing the early-stage detection of kidney disease." (PMID 34436062, 2021). "Yet, median albumin excretion rate was lower than in the target population, likely because patients with advanced renal disease were excluded from CVOTs." (PMID 33971880, 2021). "Of these patients, 236 (85.5%) had significantly reduced albumin levels at the time of admission to hospital, which was likely indicative of pre-existing chronic liver or renal disease." (PMID 34574044, 2021). "The test that has been incorporated into the Kidney Disease Improving Global Outcome guidelines (Albumin-to-creatinine ratio-ACR) uses the ratio of albumin to creatinine concentrations in a single urine sample." (PMID 34438524, 2021). "The measurements of urinary albumin/total protein excretion play key roles in the detection and classification of renal disease." (PMID 33800255, 2021). "In the present study, basophils, albumin, modification of diet in renal disease (MDRD), and LDH were confirmed to be related to the blood concentration of vitamin D." (PMID 34884121, 2021). "Particularly, increased body mass index has been correlated with oxidative stress and urinary albumin excretion in kidney disease patients, also contributing to increased cardiovascular risk." (PMID 33800425, 2021).
kidney disease (continued). "Those with kidney disease (estimated glomerular filtration rate < 60 mL/min/1.73 m2 or urine albumin to creatinine ratio ≥ 3 mg/mmol) were excluded." (PMID 33850209, 2021). "To date, 10% FCS continues to be the most common media supplement employed in clinical trials for kidney disease, although some consideration has been given to the use of xenogeneic-free media such as hPL (5 or 10%), human serum albumin (HSA) and a CDM." (PMID 34616756, 2021). "Under proteinuric condition, tubular handling and response to the excessive albumin has significant implications in kidney disease." (PMID 32641688, 2020). "Certain biomarkers, such as albumin and creatinine which were originally known as early markers of renal disease, have recently been indicated in large epidemiological studies to be independent predictors of CVD in adults." (PMID 32231008, 2020). "In our study, Acinetobacter and uncultured Moraxellaceae were related to better kidney function and higher levels of plasma haemoglobin and serum albumin in all kidney diseases." (PMID 33004860, 2020). "Activity of renal disease and preservation of renal function will be assessed by renal function measurements (glomerular filtration rate, urinary albumin:creatinine ratio, and urinary MCP-1:creatinine ratio)." (PMID 32088663, 2020). "This was the case for the albumin/creatinine index, which is an early screener for kidney disease, the intake of opioids, and social needs, as highlighted earlier." (PMID 32854694, 2020). "In follow-up analyses, we saw little evidence of shared genetic underpinnings with the exception of urinary albumin-to-creatinine ratio (Rg = 0.64; SE = 0.22; P = 0.0042), a biomarker of kidney disease." (PMID 32227112, 2020). "Kidney disorders were described according to the presence of reduced estimated glomerular filtration rate (eGFR) and/or higher urinary albumin to creatinine ratio (UACR)." (PMID 32337292, 2020). "Supporting this view, our results show that lithium decreases the development of TII induced by albumin overload and, consequently, the progression of renal disease." (PMID 31002704, 2019). "Urinary albumin to creatinine ratio (ACR) is an important prognostic indicator for progression of renal disease, and cardiovascular events." (PMID 31803059, 2019). "Our results also revealed a significant correlation between PPP1R2P1 (A/G) and albumin/globulin ratio, which is an indicator of liver and kidney disorders." (PMID 31827636, 2019). "Our analysis supports the observations of others, that men are over-represented in the latter stages of CKD24, with our model predicting a slower progression of kidney disease for women in the unmeasured urine albumin and normoalbuminuria cohorts." (PMID 36225973, 2019). "Microalbuminuria, defined by urinary albumin-to-creatinine ratio, is a well-known early marker for the progression of kidney diseases." (PMID 31888083, 2019). "Relative to controls, serum levels of urea, creatinine, phosphate, and OPG also increased with advancing kidney disease, while albumin levels reduced most markedly in the HD cohort." (PMID 31519772, 2019). "Taken together, oxidized albumin is a useful marker for oxidative stress-induced kidney disease, and appear to be an advanced marker compared to 8-isoprostane." (PMID 31197181, 2019). "Previous studies have indicated that low albumin in NS patients is related to renal injury and prognosis of kidney disease." (PMID 30003098, 2018). "Those with urine albumin excretion over 30 mg/g creatinine were considered as having albuminuria, and eGFR was calculated using modified diet in renal disease (MDRD) formula." (PMID 30729117, 2018). "Urine albumin-to-creatinine is suggested for albuminuria screening to assess kidney diseases and related with glomerular damage and progressive renal dysfunction." (PMID 29849929, 2018).
kidney disease (continued). "In the 17 patients with active renal disease, creatinine levels were between 0.63 and 1.63 mg/dl; urinary proteins were between 0.4 and 8.8 g/24 h and serum albumin was between 2.4 and 3.6 g/dl." (PMID 29422069, 2018). "The role of the FcRn in renal physiology (albumin handling) and renal disease has been explored in numerous publications involving genetic knockouts and pharmacological interventions." (PMID 28664159, 2017). "Patients with an estimated glomerular filtration rate through the modification of diet of renal disease (MDRD) formula < 30 mL/min/1.73 m2 or urinary albumin excretion > 300 mg/24 h will be excluded." (PMID 28874181, 2017). "Age, hemoglobin, albumin, urea, creatinine levels, primary kidney disease subclass, and HD duration are the major determinants for functional status in HD patients." (PMID 29282123, 2017). "This study provides the strongest evidence on the significance of serum albumin levels on the immunogenicity of HB vaccination in kidney disease patients." (PMID 29201314, 2017). "However, urinary albumin excretion may be modified by smoking, in which case adjustment for it could lead to the introduction of bias in the estimate of the association between smoking and kidney disease progression." (PMID 27118687, 2016). "This test should have the ability to detect kidney disease with a threshold of 1+ proteinuria, but dipstick tests measure levels of albumin, and if urine is diluted the accuracy of these tests is affected." (PMID 25798180, 2015). "Albuminuria is a strong and independent predictor of kidney disease progression but the mechanisms of albumin handling by the kidney remain to be fully defined." (PMID 26333830, 2015). "This means that the change in integrity of albumin excreted in the urine in renal disease is the primary factor governing the relative increase in intact albuminuria." (PMID 26010895, 2015). "Albuminuria is one of the hallmarks of kidney disease and thus there is intense interest in determining precisely how the kidney handles albumin under physiologic and disease conditions." (PMID 26333830, 2015). "The role of albumin overload in proximal tubules (PT) in the development of tubulointerstitial injury and, consequently, in the progression of renal disease has become more relevant in recent years." (PMID 25302946, 2014). "The 6-variable modification of diet in renal diseases formula fairs better as it takes into account the serum albumin and blood urea nitrogen, too." (PMID 25520843, 2014). "Albumin excretion rate, a known marker of kidney disease progression, correlated with urinary MCP-1." (PMID 25142123, 2014). "Based on the accuracy of the semi-quantitative urine dipstick, the KDIGO CKD Guidelines suggest the use of either a spot protein-to-creatinine or spot albumin-to-creatinine ratio for kidney disease screening." (PMID 25189092, 2014). "The progression of renal disease involves several factors including tubulointerstitial injury induced by albumin overload in PTs." (PMID 25302946, 2014). "Presently, the definitive urinary biomarkers for kidney diseases include albumin and β2-microglobulin." (PMID 23403919, 2013). "Low levels of serum albumin, abnormal UA, Ccr and proteinuria were also frequent due to renal disorder." (PMID 23006903, 2012). "It has been shown that effective seroconversion after vaccination of HD patients depends on age, body mass, serum albumin concentration, type of dialyzer, duration of RRT, and underlying kidney disease." (PMID 22863216, 2012). "Urinary albumin, the predominant urinary protein in most proteinuric renal diseases, can be evaluated using an albumin-specific dipstick, immunochemical techniques, and size-exclusion high-performance liquid chromatography." (PMID 22844592, 2012). "In certain renal diseases large proteins such as albumin leak into urinary space and the amount of secreted protein very much depends on the specific disease." (PMID 23300915, 2012).
kidney disease (continued). "In the present study, it is clear that CDDP exposure resulted oxidative stress, genomic DNA damage, apoptotic cell death in kidney, increased serum creatinine and blood urea, and decreased levels of albumin and total protein biomarkers for kidney disease." (PMID 22849573, 2012). "Serum creatinine and the albumin:creatinine ratio in urine are in clinical use as biomarkers of kidney disease." (PMID 23300915, 2012). "Age, sex, cardiovascular risk factors, possible biochemical and health consequences of kidney disease (hemoglobin, phosphate, and albumin levels; physical and mental health problems)." (PMID 21146270, 2011). "In proteinuric kidney diseases, excess exposure of proximal tubular cells to albumin, FFA bound to albumin or cytokines such as TNFα is detrimental." (PMID 21966476, 2011). "Ideally, we could have included other variants known to be related to the progression and severity of renal disease, such as those within inflammatory cytokine IL-6 and polymorphisms identified in a recent genome-wide association study as significantly associated with urine albumin excretion." (PMID 21054877, 2010). "Obese Zucker rats had significantly higher levels of plasma creatinine and urine albumin excretion, relative to lean age-mates, indicating impaired renal function and advancing renal disease." (PMID 20490358, 2010). "Renal disease activity was monitored by measuring urine protein/creatinine ratio (PCR), serum albumin and a composite outcome of renal remission." (PMID 19828047, 2009). "The 2020 Kidney Disease Outcomes Quality Initiative (KDOQI) guidelines for CKD nutrition recognize that albumin and/or serum prealbumin may be considered supplemental tools for assessing nutritional status." (PMID 41457350, 2026). "Furthermore, changes in albumin levels in kidney disease and during dialysis can affect its protein-binding capacity." (PMID 40729346, 2025). "While there is considerable overlap between serological indicators of liver and kidney dysfunction, the ratios of circulating albumin to globulin (ALB/GLOB) and blood urea nitrogen to creatinine (BUN/CRE) are more closely associated with kidney disease or damage." (PMID 40766078, 2025). "Furthermore, oxidized albumin, particularly the form oxidatively modified at the Cys34 residue, has emerged as a promising marker for kidney disease progression, indicating its potential for quantitative evaluation." (PMID 41226246, 2025). "Since these two entities are interrelated and both promote the development and progression of kidney disease, it might be useful to evaluate not only albumin levels, but also the albumin’s redox state, for the prognosis of kidney disease." (PMID 40244241, 2025). "Albumin is a strong predictor of mortality in patients with kidney disease." (PMID 41295863, 2025). "However, there are still discussions supporting the straightforward use of albumin as a nutritional indicator for assessing kidney disorders." (PMID 40142234, 2025). "In healthy individuals, the albumin content in urine is typically less than 30 mg/g creatinine, and any value higher than this may indicate potential kidney disease." (PMID 39202190, 2024). "This was observed independently of factors that might influence serum albumin levels, such as liver or renal disease, acute inflammation, or nutritional status." (PMID 39010980, 2024). "Although the determinations of creatinine and albumin from 24 h urine samples are considered the gold standard and widely used laboratory tests for kidney disorders, these tests pose challenges, including inconvenience for patients and potential low adherence to instructions." (PMID 39202190, 2024). "However, eGFR is more a marker of kidney disease per se, and urinary albumin is more a marker of systemic vascular damage or microvascular disease." (PMID 39438792, 2024).